MYCN (MYCN proto-oncogene, bHLH transcription factor)
Diseases named in the same sentence as MYCN in open-access papers (continued):
Sharing a sentence is not in itself a finding about the gene and the disease.
tumor (continued). "It was reported that MYCN amplification is associated with 1p36 LOH, which is harboured in a proximal tumour suppressor region." (PMID 35137546, 2022). "Previous studies have attributed functional consequences to ARID1A-loss in the context of MYCN-amplified tumours, and some authors have postulated ARID1A as the main driving tumour suppressor in 1p36-lost MYCN-amplified cases." (PMID 36057593, 2022). "Other significantly upregulated genes such as SALL4, FOXM1, MYCN, MEP1A and MYBL2 have also been reported to be significantly elevated in HCC and associated with tumor progression." (PMID 36212481, 2022). "Some of the existing positive feedback loops between other tumor-dependent genes and MYCN have been reported, and our study has provided additional evidence for MYCN networks." (PMID 36539767, 2022). "Between 2010 and 2015, 127 tumor samples were detected MYCN amplification status simultaneously by FISH and IHC (MYCN antibody: #51705, Cell Signaling Technology) at SCMC." (PMID 35820898, 2022). "Here we show that targeting FA uptake effectively inhibits MYCN-induced glycerolipid accumulation and tumor growth, suggesting that FA transport is critical for these functions." (PMID 35764645, 2022). "MYCN overexpression reprograms the tumor cells towards a stem-like phenotype that promotes proliferation and cell growth, while inhibiting cell differentiation and apoptosis." (PMID 35890348, 2022). "When combining these two drugs, we observed a 60% reduction in tumor growth in MYCN-amplified SK-N-DZ-driven tumors." (PMID 35484422, 2022). "Of note, ectopic MYCN expression resulted in increased tumor volume and weight in xenograft model but IGF2BP1 silencing largely abrogated this effect." (PMID 35346372, 2022). "In clinical settings, tumor MYCN status is detected by fluorescence in situ hybridization (FISH) on malignant tissues from tumor biopsies or metastatic cells via bone marrow aspiration/biopsy." (PMID 35681607, 2022). "This gene has been suggested as a tumor suppressor in high-risk NB through destabilization of AURKA and MYCN." (PMID 36306349, 2022). "In vitro, in the NB cell lines TR14 and CHP212 with MYCN amplified on ecDNA, tumor cells with lower copy number were selected in response to vincristine." (PMID 36123406, 2022). "In another study, by targeting miR-520f, neuronal apoptosis inhibitor protein produced drug resistance through apoptosis inhibition in non-MYCN amplified tumor cells." (PMID 35392988, 2022). "Taken together, our study showed that C1GALT1 high expression is an independent prognostic factor and predicts better survival outcomes for NB patients, complementary to age of patients, differentiation status of tumor, MYCN status, and clinical stages." (PMID 35169131, 2022). "Gene group 2 displayed a significant upregulation of E2F transcription activators (E2F1, E2F2, E2F3, and E2F6) and tumor-specific transcription factors (MYCN, RUNX1, and GABPB1) in advanced Rb." (PMID 35626705, 2022). "The importance of PRC2 in MYCN-induced tumor formation is shown by the suppression of tumor development in response to EZH2 inhibition." (PMID 35681734, 2022). "MYCMI-7 potently induces growth arrest/apoptosis in tumor cells in a MYC/MYCN-dependent manner and downregulates the MYC pathway on a global level as determined by RNA sequencing." (PMID 36874405, 2022).
tumor (continued). "Here we confirm the cooperation between TWIST1 and MYCN in defining a transcriptional program in NB supporting in vitro cell proliferation and in vivo tumor growth." (PMID 35022561, 2022). "In the method developed by the Children’s Oncology Group (COG), age at diagnosis, disease stage, tumor histology by the International Neuroblastoma Pathology Classification (INPC) criteria, MYCN status, and DNA ploidy are employed to stratify risk groups." (PMID 35740540, 2022). "Among other members of this exporter family representing downstream targets of MYCN, ABCG2 is unique in its strong association with a cancer stem cell-enriched tumor phenotype exhibiting inherently high resistance to chemotherapeutic agents." (PMID 35163672, 2022). "The PROTAC compound JQAD1 selectively targets p300 protein for degradation, reduces the transcription of critical oncogenes such as MYCN, and induces neuroblastoma cell apoptosis in vitro and tumor growth inhibition in mouse models." (PMID 35836809, 2022). "The analysis showed three copies of DEK and four copies of MYCN, confirming the presence of tumor DNA." (PMID 35340648, 2022). "Treatment of NCI-H526 xenografts with a dose of either 50 or 100 mg/kg of GSK126 barely affected MYCN expression and tumor growth." (PMID 35013218, 2022). "We further confirmed EZH2 and MYCN protein levels by immunoblot in 18 primary tumor samples isolated from TH-MYCN mice." (PMID 35013218, 2022). "As an important transcription factor, N-myc plays an important role in the tumor biological characteristics of MYCN positive NB." (PMID 36311753, 2022). "MYCN amplification is an independent prognostic factor for identifying rapid tumor progression and predicting the poor prognosis of patients with NB." (PMID 35757140, 2022). "In this scenario, MYCN certainly represents an ideal therapeutic target given its correlation with rapid tumor progression, poor prognosis and the limited expression in normal cells and tissue, suggesting high tolerability for an MYCN-specific approach." (PMID 36139583, 2022). "We and others have recently demonstrated that CUL4B regulates the expression of several tumor suppressors, including MYCN, PIK3CA, HER2, SOX4, C-MYC and CDH2 at the posttranscriptional level." (PMID 35784474, 2022). "CHK1 inhibitors can well inhibit the protective effect of ATR/CHK1 pathway on MYCN positive tumor cells." (PMID 36311753, 2022). "Patients with higher risk disease, which was categorized as patients with a stage 4 tumor at an age over 1 year or stage 1, 2, 3, or 4S tumors with MYCN amplification, also had lower N-cadherin mRNA expression compared to low-risk patients (p = 0.048)." (PMID 35574403, 2022). "The standard procedure for the detection of NB MYCN amplification is tumour biopsies from the primary site of presentation or metastatic sites, including the bone marrow and subsequent fluorescence in situ hybridisation (FISH)." (PMID 36362869, 2022). "As expected, administration of DZNep, which depleted EZH2 and MYCN, markedly inhibited proliferation of all the tumor cells examined, while administration of the enzymatic inhibitors (GSK126 and EPZ6438) exhibited minimal effects on Kelly and BE-2C cells." (PMID 35013218, 2022). "Primary NB tumor harbored, in addition to high-grade amplification of six loci besides MYCN, the atypical 5p15 gain containing TERT gene." (PMID 34830942, 2021). "These previous findings suggested NLRR1 as an executer protein for aggressiveness of NB under MYCN regulation and a possible therapeutic target to control tumor growth." (PMID 34277416, 2021). "Especially as in response to chemotherapy or molecules inducing neuronal differentiation, such as retinoic acid or neurotrophins, tumor cells can overcome MYCN-driven differentiation blocks, undergo apoptosis or cellular senescence." (PMID 34503120, 2021). "Tumour samples from Th‐MYCN, Alk‐F1178S;Th‐MYCN and Rosa26_Alkal2;Th‐MYCN mice were harvested and RNA‐Seq data compared." (PMID 33411331, 2021).
tumor (continued). "Multiple single-copy gain events occurred on 2p24 in the primary tumour at diagnosis that developed into a MYCN amplification (16 copies) at the time of tumour resection." (PMID 34815394, 2021). "It is interesting that the ALKAL2‐induced transcriptomic response observed in Rosa26_Alkal2;Th‐MYCN is weaker than that seen in Alk‐F1178S;Th‐MYCN tumours." (PMID 33411331, 2021). "To understand the underlying mechanism of this therapeutic intervention on NB tumour growth, we investigated gene expression in treated tumours from both Rosa26_Alkal2;Th-MYCN and Alk-F1178S;Th-MYCN relative to untreated controls." (PMID 34819497, 2021). "Here we identified two tumours which were biallelically null for RB1 that also harboured focal MYCN amplifications, in the case of PD34256 an amplification of 168-fold, while PD37495 was amplified 51-fold." (PMID 33670346, 2021). "Lastly, we benchmark NB organoids isolated from PDXs against clonal expansion of cell lines and cell line-derived xenografts and investigate the role of tumour-biological factors (soluble factors, MYCN)." (PMID 33578855, 2021). "Let-7 miRNAs are tumor suppressors post-transcriptionally repressing MYCN expression, as well as feedback repressing LIN28 expression in the MYCN/LIN28/let-7 pathway." (PMID 35008302, 2021). "Kinetic studies of MYCN activation in NB have been performed to identify tumor-specific dependencies among CRC TFs, drawing the first dynamic chromatin and transcriptional landscape of MYCN perturbation in NB." (PMID 34771690, 2021). "Taken together, our immunohistochemical analyses show that BAY 1895344 induces a robust apoptotic response in the tumour together with a strong host immune response in Alk/MYCN-driven NB." (PMID 34819497, 2021). "CB1001 is a patient with high-risk disease that includes a clonal MYCN amplification, and for whom 5 SCNA profiles were available comprising 4 regions from the primary tumour and 1 from a metastatic renal infiltration." (PMID 34815394, 2021). "According to the cIMPACT WC2,these neoplasms should be considered as a novel molecular group (SC-EPN-MYCN) to be assessed using MYCN amplification assays in all newly diagnosed SC-EPNs." (PMID 34885237, 2021). "According to The Cancer Genome Atlas (TCGA), MYC amplification occurs in 21% of all tumor samples, whereas that of the MYCN and MYCL paralogs are much less frequent." (PMID 34503295, 2021). "Apart from tumour cases with MYCN gene amplification, the immune system dysregulation can occur as a consequence of other events leading to increased MYCN activity (mRNA and protein stabilization, mi-RNA alteration)." (PMID 34195095, 2021). "We assessed the ability of such compounds to disrupt the interaction between AURKA and N-Myc in vitro, using Surface Plasmon Resonance competition assays, and in tumor cell lines overexpressing MYCN, by performing Proximity Ligation Assays." (PMID 34884931, 2021). "Pharmacological targeting of MYCN, albeit so far, only indirectly, is defined by reduced tumor growth in vitro and in vivo." (PMID 33404859, 2021). "Cell line #3456 was generated from an Alk‐F1178S;Th‐MYCN NB, while cell line #3540 was generated from Rosa26_Alkal2;Th‐MYCN tumour tissue." (PMID 33411331, 2021). "The molecular consequences of MYCN overexpression in this aggressive pediatric tumor have been studied for decades, but thus far, our understanding of the early initiating steps of MYCN-driven tumor formation is still enigmatic." (PMID 34638267, 2021). "The finding of MYCN amplification, segmental chromosomal alterations, and histological features of undifferentiated tumour cells with a high Mitosis-Karyorrhexis index are all markers of aggressive disease." (PMID 33808071, 2021). "Some genetic markers for NB include GD2 synthase mRNA, state of chromosome 1 (1p), MAGE and BAGE genes, and MYCN amplification; tumor-specific antigens include GD2, CD81, CD56, and CD45." (PMID 34445807, 2021).
tumor (continued). "10% of Rosa26_Alkal2;Th‐MYCN tumours (n = 20 examined) and 30% of Alk‐F1178S;Th‐MYCN (n = 10 examined) exhibited involvement of one or more adrenal gland." (PMID 33411331, 2021). "MYCN orchestrates multiple molecular pathways for cell growth, survival, metabolism, and death, dictating cancer cell fate and tumor progression." (PMID 34011924, 2021). "For example, MYCN amplification has been observed in tumor DNA and in exo-DNA both at onset and at relapse." (PMID 33915956, 2021). "This can be compared with the restricted growth of NB tumours in Rosa26_Alkal2;Th‐MYCN when treated with lorlatinib." (PMID 33411331, 2021). "Oncogenes such as MYCN also regulate the expression of a few other dysregulated genes such as enzymes involved in altered metabolism in tumor cells." (PMID 33915740, 2021). "Remarkably, the nanomicellar combination of lenalidomide–fenretinide suppresses tumor growth in a MYCN-amplified neuroblastoma tumor mediated by increased expression of GD2, a disialoganglioside expressed on tumors of neuroectodermal origin." (PMID 34737957, 2021). "Tumours with high levels of this complex genome arrangement show a positive correlation in the frequency of MYC/MYCN amplifications." (PMID 34195095, 2021). "In tumors with activated MYC or MYCN, the high demand for growth and biomass accumulation required for tumor progression is achieved by metabolic reprogramming." (PMID 34183658, 2021). "Taken together, a picture emerges where DNA copy number affected regions seem to be embedded within the tumor genome under the selective pressure to increasingly support MYCN activity in these cells." (PMID 34945759, 2021). "We investigated the role of MYCN in regulating the protein cargo of extracellular vesicles (EVs) secreted by tumour cells that can be internalized by recipient cells with functional consequences." (PMID 34847775, 2021). "In general, the transcriptional signature of Rosa26_Alkal2;Th‐MYCN tumours was less pronounced but overall very similar to the signature in Alk‐F1178S;Th‐MYCN tumours." (PMID 33411331, 2021). "Another interesting study showed that the combination treatment of cells that were RB1 wildtype with MYCN amplification and chemoresistant with Panobinostat and bortezomib or carboplatin inhibited tumor cell growth." (PMID 34680394, 2021). "BIRC5 and HK2 showed higher expression in MYCN amplified cell lines and tumor tissues consistently, whereas GRID2 and RNASEL showed the opposite trends." (PMID 34746127, 2021). "We observed a 366-fold increase in MYCN mRNA expression in the tumour with 168 copies of MYCN (PD34256) and 11- to 21-fold increase in expression in 4 tumours with 2 or 3 copies." (PMID 33670346, 2021). "This activity correlates with tumor regression and prolonged survival in a MYCN-driven NB model in mice." (PMID 34885651, 2021). "MYCN amplification results in increased cellular proliferation and growth, decreased apoptosis, poor differentiation, and increased vascularity of the tumours." (PMID 33968920, 2021). "While these clinical studies supported a potential role for AURKA inhibition in the management of patients with advanced NB, patients with MYCN/MYC-driven tumours still showed poor outcomes despite treatment with this regimen." (PMID 34195095, 2021). "Cells transformed exclusively with PAX3-FOXO1 generated tumours after a longer period of time than those also expressing MYCN." (PMID 34445233, 2021). "MYCN-dependent tumors mostly occur as aggressive and deadly neoplasia, very poorly responsive to current therapies." (PMID 34508175, 2021). "Three of them, ETS1, MYCN and TFAP2A, have been previously associated with the cancer progression and all of them show tumour promoting effects." (PMID 34198662, 2021). "Downregulation of MYCN expression induces apoptosis and differentiation, reverses tumor stem-like features, and accompanies senescence in MYCN-amplified NB cells." (PMID 33404859, 2021).
tumor (continued). "Alk‐F1178S animals were bred with Th‐MYCN transgenic mice expressing MYCN under the control of the tyrosine hydroxylase (Th) promoter, and tumour development was followed." (PMID 33411331, 2021). "To determine if MYCN expression synergizes with Rb1 loss to drive a molecular program associated with NEPC, we performed bulk RNA-seq on histologically distinct tumor foci ranging from adenocarcinoma to NEPC." (PMID 34099734, 2021). "Previous characterization of Th‐MYCN tumours has identified several partial and chromosomal gains and losses." (PMID 33411331, 2021). "Since ODC1 is an established MYC target gene, we investigated the possibility of differential effects of the SNP in subsets of patients depending on the MYCN status of their tumor." (PMID 33918978, 2021). "MYCN is amplified in some SHH-MB tumor cells, such that MYCN expression was significantly correlated with SHH-MB tumor purity, as expected (Spearman’s correlation coefficient = 0.3265, p = 6.193 × 10−7)." (PMID 35008302, 2021). "Otherwise, ARID1A acts as a proximal tumour suppressor, promoting tumorigenesis via MYCN amplification in tumours harbouring larger 1p36 deletions." (PMID 34884690, 2021). "The overexpression of MYCN/MYC target genes in subtype 2 tumors, and the assignment of 10 out of 11 MYCN-amplified tumors to subtype 2 tumors (the remaining MYCN-amplified tumor being unclassified) suggest that MYCN/MYC play an important role in this subtype." (PMID 34552068, 2021). "One mouse of genotype Rosa26_Alkal2;Th-MYCN was identified with an abdominal tumour (∅ > 14 mm) 100 days after initial treatment start and subjected to an additional 14 day regimen, exhibiting a second complete response." (PMID 34819497, 2021). "The MYC family member c-MYC and MYCN are the most frequently deregulated oncogenes in human cancer and promote tumor progression through multiple levels of mechanisms in particular reprogrammed metabolism." (PMID 34235156, 2021). "Immunohistochemical analysis of tumours in Rosa26_Alkal2;Th-MYCN and Alk-F1178S;Th-MYCN mice confirmed a dramatic apoptotic response, as measured with cleaved caspase 3 (CC3), after 3 days of treatment." (PMID 34819497, 2021). "In those studies, inhibition of PI3K/AKT/mTOR induced destabilization of the MYCN oncoprotein and triggered anti-tumor effects 41,42." (PMID 33390782, 2021). "The A-NB94 trial was the first in Austria to stratify therapy intensity according to tumor staging, patient’s age, and MYCN amplification status, the latter being a biologic marker turning otherwise low-risk tumors into high-risk disease." (PMID 33540616, 2021). "RNA-Seq analysis indicated a downregulation of 603 and 2220 genes in Alk-F1178S;Th-MYCN and Rosa26_Alkal2;Th-MYCN tumours, respectively (log2 fold change of 1.5 at 1% FDR)." (PMID 34819497, 2021). "Two eyes (Cases 3 and 48) displayed SCNAs in addition to focal MYCN amplification in both the AH and matched tumor tissue, while the other two eyes (Cases 10 and 31) only displayed MYCN amplification." (PMID 34283049, 2021). "These theories were further fuelled by the discovery of a subset of Rb tumours with amplification of MYCN which initially appeared to be mutually exclusive with RB1 mutations." (PMID 33670346, 2021). "Cells dissociated from NB tumour tissue arising from either Rosa26_Alkal2;Th‐MYCN and Alk‐F1178S;Th‐MYCN were subjected to increasing doses of either brigatinib or lorlatinib." (PMID 33411331, 2021). "The expression of MYCN was increased gradually with tumor stage development and upregulated in poor or undifferentiated tumors compared with normal tissues, which was significantly associated with poor clinical outcome." (PMID 33500560, 2021). "MYCN amplifications are also present in G4 tumours, however, this is generally at a much lower level compared with the SHH subgroup." (PMID 34195095, 2021).